TET3 (tet methylcytosine dioxygenase 3)
Diseases named in the same sentence as TET3 in open-access papers (continued):
Sharing a sentence is not in itself a finding about the gene and the disease.
asthma (1 paper, 2023). "Smooth muscle cell-specific knockout of Tet3 in mice leads to loss of intragenic 5-hydroxymethylcytosine, accumulation of spurious transcripts and TLR7/8-mediated lung inflammation resembling asthma in human lung samples." (PMID 36539616, 2023). "Our study reveals that spurious transcripts in Tet3-deficient mouse SMCs lead to activation of TLR7/8 signaling-dependent innate immune responses and massive lung inflammation, resembling human asthma, offering perspectives to treat various lung diseases." (PMID 36539616, 2023). "The discovery that loss of Tet3 causes an asthma-like phenotype strongly suggests that the reduction of 5hmC in airways of human asthma patients is not an epiphenomenon but is causally involved in the pathogenesis of asthma." (PMID 36539616, 2023).
Brachycephaly (1 paper, 2023). An abnormality of skull shape characterized by a decreased anterior-posterior diameter. "This case and previous reports of patients with TET3-related craniofacial involvement including brachycephaly and asymmetric skull shapes point out towards a possible role of TET3-variants in the dysregulation of gene expression during suture development." (PMID 38318288, 2023).
chronic myeloid leukaemia (1 paper, 2023). "In a chronic myeloid leukaemia cell line (K562), the enhancer for TET3 was identified as a strong target for HIF1α binding, with TET3 expressed at higher levels than TET1 and TET2 in hypoxia." (PMID 37705055, 2023).
Cirrhosis (1 paper, 2023). A chronic disorder of the liver in which liver tissue becomes scarred and is partially replaced by regenerative nodules and fibrotic tissue resulting in loss of liver function. "Serum TET3 level in cirrhosis cases (median 1148.09, range 362.64–1451.11 ng/mL) was significantly higher than that in hepatitis (median 268.10, range 133.97–900.56 ng/mL) and controls (median 127.58, range 96.99–163.7 ng/mL), respectively." (PMID 37076545, 2023).
clear cell adenocarcinoma (1 paper, 2019). A malignant neoplasm composed of glandular epithelial clear cells. "Besides, TET3 expression is higher in each specific histology, including serous adenocarcinoma (P = 0.054), endometrioid adenocarcinoma (P = 0.023), clear cell adenocarcinoma (P = 0.016), and mucinous adenocarcinoma (P = 0.061) in comparison with ovarian normal tissues." (PMID 31656201, 2019).
depression (1 paper, 2023). "In the depression susceptible model, we found a continual decrease in the DNA modifying proteins (Dnmt3a, Tet2, and Tet3) while resilient animals display TDG returning to baseline." (PMID 37228107, 2023). "Of particular interest, the DNA modifying proteins Dnmt3a, Tet2, and Tet3 were found, suggesting that the loss or reduced expression of epigenetic machinery could be a key contributor to stress-induced depression." (PMID 37228107, 2023). "Furthermore, in our depression susceptible model where 5hmC continuously decreased along the ASDS-CSDS-LSDS continuum, the DNA modifying proteins Dnmt3a, Tet2, and Tet3 were found." (PMID 37228107, 2023).
embryonic carcinoma (1 paper, 2014). "We depleted TET1, TET2, and TET3 in a pluripotent embryonic carcinoma cell model and examined the impact on genome-wide 5mC, 5hmC, and transcriptional patterns." (PMID 24958354, 2014).
gingivitis (1 paper, 2022). A disorder involving inflammation of the gums; may affect surrounding and supporting structures of the teeth. "This review identified that exRNA has the greatest diagnostic potential, with four biomarkers (SPRR1A, lnc-TET3-2:1, FAM25A, CRCT1) displaying sensitivity of >71% and specificity of 100% in the assessed samples (p < 0.001) for gingivitis." (PMID 35453967, 2022).
Granuloma (1 paper, 2020). A compact, organized collection of mature mononuclear phagocytes, which may be but is not necessarily accompanied by accessory features such as necrosis. "Liver damage induced downregulation of DNMT1 and TET3 expression considering granulomas number." (PMID 32078636, 2020). "TET3 correlated positively with TET2, DNMT1, and negatively correlated with granulomas number and miR31-3p and 122-3p expression." (PMID 32078636, 2020). "Correlation analysis among the expression of TET1, 2 and 3 and DNMT1, 3A and 3B indicated that there was a negative correlation between DNMT1 and TET3 gene expression and granuloma number in EBi3-/-I." (PMID 32078636, 2020). "In this work it was observed that there is a negative correlation between this miRNA and the DNA methyltransferase and demethylase genes (DNMT1 and TET3) and positive with the number of granulomas found in the liver of EBi3-/-I mice, which does not occur in WTI." (PMID 32078636, 2020).
head and neck cancer (1 paper, 2018). A primary or metastatic malignant neoplasm affecting the head and neck. "Our findings provide evidence that TET3 methylation may represent a good biomarker for prediction of recurrence in early-stage head and neck cancers." (PMID 29849955, 2018).
Hypertension (1 paper, 2024). The presence of chronic increased pressure in the systemic arterial system. "In contrast, anti-Dnmt3a alone did not manage hypertension as effectively as the combined treatment of anti-Dnmt3a and anti-Tet3." (PMID 39595187, 2024).
ischemic disease (1 paper, 2024). Lack of blood supply to an area of the body, resulting in impairment of tissue oxygenation. "Studies on TET1 and TET3 in angiogenesis are mainly concentrated in cancer and ischemic diseases, and its research in diabetic complications, especially DR, is scarce." (PMID 38172938, 2024).
large cell lung cancer (1 paper, 2024). "The findings revealed significantly higher expression levels of TET3 protein in lung adenocarcinoma A549 and lung squamous cell carcinoma SKMES1 compared to normal controls and large cell lung cancer cell lines." (PMID 39104395, 2024).
liver cancer (1 paper, 2024). An epithelial or non-epithelial malignant neoplasm that arises from the liver. "To further investigate whether TET2 regulates cGAS expression, we overexpressed Tet1, Tet2, and Tet3 in liver cancer cells, respectively." (PMID 38177099, 2024).
liver cirrhosis (1 paper, 2023). "TET3-FIB-4 index cut-off value of 0.52 had a high PPV of 100% for ruling in patients with liver cirrhosis." (PMID 37076545, 2023). "With an optimal cut-off value of 201.62 ng/mL, TET3 level had a high PPV of 100% and a NPV of 87.90% for predicting the risk of liver cirrhosis." (PMID 37076545, 2023).
liver diseases (1 paper, 2024). "There, TET3 can activate genes through DNA demethylation, which may reflect in the development of a variety of liver diseases." (PMID 39201990, 2024).
malignant pleural mesothelioma (1 paper, 2016). A malignant neoplasm that arises from mesothelial cells in the pleura and shows a diffuse growth pattern. "However, this decrease was significant in the rat for TET1 and TET3 between preneoplastic and neoplastic cell lines, and in humans for TET2 between normal mesothelial cells (MC) and malignant pleural mesothelioma cell lines (MPM)." (PMID 27129173, 2016).
medulloblastoma (1 paper, 2021). A malignant, invasive embryonal neoplasm arising from the cerebellum. "The oncogenic effect of mutations in the fusion genes such as ARID1A, PVT1, GFI1, MYCN, DNMT1, and TET3 has been identified in various tumors including medulloblastomas to regulate tumorigenesis, suggesting that the predicted inframe fusion proteins may possess oncogenic potential." (PMID 33681213, 2021).
metabolic syndrome (1 paper, 2024). A cluster of metabolic risk factors for CARDIOVASCULAR DISEASES and TYPE 2 DIABETES MELLITUS. "Our results demonstrate an essential role for TET3 in the regulation of skeletal muscle insulin sensitivity and suggest that TET3 may be used as a potential therapeutic target for the metabolic syndrome." (PMID 38216792, 2024).
metastatic melanoma (1 paper, 2017). A melanoma that has spread from its primary site to another anatomic site. "Treatment of the metastatic melanoma cell line SK-MEL-1, which expressed very low levels of TET2 and TET3, with LY9702161, elevated their expression levels." (PMID 27852070, 2017).
microphthalmia (1 paper, 2017). Congenital or developmental anomaly in which the eyeballs are abnormally small. "While the PLM and BrdU incorporation results suggest that elongation of the cell cycle during early retinal development underlies microphthalmia in tet2-/-;tet3-/- mutants, apoptosis of RPCs or newly differentiated neurons could also contribute." (PMID 28926578, 2017). "No increase in apoptotic cells was detected in tet2-/-;tet3-/- mutant until after 3dpf, indicating that apoptosis is unlikely to account for microphthalmia in tet2-/-;tet3-/- mutants." (PMID 28926578, 2017).
neuroblastoma (1 paper, 2024). Neuroblastoma (NB) is the most common solid, extracranial childhood tumor. "We report the results of an unbiased transcriptome analysis of the neuroblastoma-derived cell line; Neuro2A, in which Tet3 was silenced." (PMID 38227585, 2024). "We addressed this by analysing the effects of Tet3 genetic silencing upon the transcriptome of the neuroblastoma-derived cell line, N2A." (PMID 38227585, 2024). "To begin to address this, we therefore investigated the transcriptional and functional roles of TET3 in the neuroblastoma cell line, Neuro2A (N2A), and have here identified its importance in the regulation of mitochondrial function and respiration." (PMID 38227585, 2024).
neuropathic pain (1 paper, 2023). Chronic pain caused by damage to nerve fibers. "In contrast, increased methylation levels and mRNA levels of TET1 and TET3 were linked to augmented pain hypersensitivity and allodynia in inflammatory and neuropathic pain models." (PMID 37108466, 2023).
ovarian serous carcinoma (1 paper, 2019). "There was more TET3 gain and diploid but less deletion in ovarian serous carcinoma." (PMID 31656201, 2019).
ovarian tumors (1 paper, 2019). "TET3 is up-regulated in ovarian tumors, while TET1 doesn’t change." (PMID 31656201, 2019).
pancreatic ductal adenocarcinoma (1 paper, 2025). An infiltrating adenocarcinoma that arises from the epithelial cells of the pancreas. "This study identifies the DNA demethylase TET3 as a key regulator of lipogenic metabolism in pancreatic ductal adenocarcinoma (PDAC)." (PMID 40567112, 2025).
papillary thyroid carcinoma (1 paper, 2022). "We further selected the cancer foci and adjacent normal tissues of 5 patients with papillary thyroid carcinoma using a random number method and verified the expression of TET3 is higher in cancer foci." (PMID 35755313, 2022). "We transfected two independent short hairpin RNA (shRNA) targeting TET3 into BCPAP and TPC-1, two classic papillary thyroid carcinoma cell lines, to inhibit the expression of TET3, and then verified the repression of TET3 expression by Western blot." (PMID 35755313, 2022). "It is suggested that the abnormal expression of DNA demethylase TET3 may play an important role in the occurrence and development of papillary thyroid carcinoma by regulating the metabolism of 5mC to 5hmC in DNA." (PMID 35755313, 2022). "To study the mechanism of elevated 5hmC level in papillary thyroid carcinoma DNA, we extracted RNA, from papillary thyroid carcinoma and adjacent normal tissues, and detected the expression levels of TET3 in these 20 samples by real-time quantitative PCR (real-time PCR)." (PMID 35755313, 2022).
renal clear cell carcinoma (1 paper, 2020). "For example, in renal clear cell carcinoma, the expressions of TET1, TET3, and TDG are positively correlated with that of hsa-miR-21-5p." (PMID 32637580, 2020). "For renal clear cell carcinoma samples, gene set enrichment analysis (GSEA) Kyoto Encyclopedia of Genes and Genomes (KEGG) pathway enrichment showed a positive correlation between expressions of TET3/TDG and miRNAs in cancer." (PMID 32637580, 2020).
secondary progressive multiple sclerosis (1 paper, 2016). A multiple sclerosis with a clinical course characterized by a progressive accumulation of neurological disability, independent of relapses, following an initial relapsing-remitting (RR) phase. "A significant downregulation of TET3 genes in secondary progressive multiple sclerosis (SPMS) patients has also been observed." (PMID 27605361, 2016).
seminoma (1 paper, 2013). A radiosensitive malignant germ cell tumor found in the testis (especially undescended), and extragonadal sites (anterior mediastinum and pineal gland). "Seminoma and EC cell lines and tumors display most prominent expression of TET1 while TET2 and TET3 are expressed at very low levels, suggesting that here TET1 is the main molecule involved in 5mC oxidation." (PMID 24386123, 2013).
serous adenocarcinoma (1 paper, 2019). An adenocarcinoma that is characterized by the presence of papillary patterns and cellular budding. "Specially, TET3 expression is higher in serous carcinoma patients with advanced stage (III-IV) comparing with those with early stage (I-II) (P < 0.0001)." (PMID 31656201, 2019).
steatosis (1 paper, 2020). Increased lipid within the cytoplasm of cells. "Compared with the control group, the mRNA and protein levels of TET1 in the two steatosis cell lines were significantly decreased, while the mRNAs of TET2 and TET3 were not significantly changed." (PMID 32577122, 2020).
synovial sarcoma (1 paper, 2025). "We first investigated whether the genes that regulate DNA methylation (DNMT1, DNMT3A, DNMT3B, TET1, TET2, TET3) are misexpressed, mutated, or amplified in synovial sarcoma." (PMID 40299558, 2025).
triple-negative breast carcinoma (1 paper, 2024). An invasive breast carcinoma which is negative for expression of estrogen receptor (ER), progesterone receptor (PR), and human epidermal growth factor receptor 2 (HER2). "The TET3 mRNA expression level was significantly increased after treatment with 4-HT in cells with expression of ER and GPER receptors, contrary to the triple-negative breast cancer cells." (PMID 39201247, 2024).
tumor (83 papers, 2013 to 2025). "Alternatively, and in accordance with previous studies, TET2, DNMT3A, and TET3 were sometimes observed in the myeloid or B‐cell fraction in addition to the tumor indicating it was likely an early founding mutation that occurred in a progenitor cells." (PMID 40510016, 2025). "TET1, TET3, and 5hmC levels are associated with tumor hypoxia, advanced differentiation grades, poor OS, and DFS in BC patients." (PMID 38203443, 2023). "NSUN2, NSUN5, NSUN6, DNMT3A, DNMT3B, ALYREF, and TET3 acted as tumor risk factors, and overexpression of these genes led to a poorer prognosis for ccRCC patients." (PMID 36661693, 2022). "The analysis of correlationship between TET3 and clinicopathological features showed that male patients and poor tumor differentiation were significantly associated with TET3 high expression level." (PMID 32014008, 2020). "In patients with T1 and T2 tumor stage, TET3 methylation showed a significant association with the OR for recurrence (OR = 2.64, 95% CI: 1.21–5.75, P = 0.014)." (PMID 29849955, 2018). "The methylation status of TET3 was independently associated with aggressive tumor behavior and a global effect on DNA methylation status in HNSCC." (PMID 29849955, 2018). "Histological analysis demonstrated that the levels of 5hmC, TET1 and TET3 were significantly associated with tumor hypoxia, tumor aggressiveness and poor prognosis." (PMID 26869355, 2016). "Interestingly, TET3 mutation frequency was relatively higher in the sorted neoplastic cell group and some mutations were tumor‐specific and likely subclonal." (PMID 40510016, 2025). "Elevated TET3 expression is correlated with improved 5-year survival (42%), and the tumor-suppressive role of TET3 is mechanistically linked to the 5mC hydroxylation-mediated maintenance of open chromatin states at neurodifferentiation-associated genes (e.g., PHOX2B)." (PMID 40787450, 2025). "Similar increases in association were also observed in Ad-TET3–infected tumor cells." (PMID 40794443, 2025). "In other cases, however, TET2, DNMT3A, and TET3 variants, appeared to be tumor specific." (PMID 40510016, 2025). "The association between TET3 expression and various cancer-related factors, such as pathway activity, tumor microenvironment, stemness score, immune subtype, clinical staging, and drug sensitivity, further underscores its relevance as a potential therapeutic target." (PMID 39104395, 2024). "Compared with RTMs in the normal tissue, a subset of mo-Macs in the tumor overexpressed TET3 and NLRP3, consistent with mouse scRNA-Seq studies." (PMID 40794443, 2025). "Conversely, TET3 mRNA transcript levels were greater in tumor tissue and positively correlated with tumor progression." (PMID 40116537, 2025). "Overall, mutated genes identified in the tumor‐enriched cohort were concordant, with recurrent variants identified in TET2, DNMT3A, RHOA, IDH2, and TET3." (PMID 40510016, 2025). "These TET3-driven programs in TAMs likely contribute to immunosuppression and tumor progression in NSCLC." (PMID 40794443, 2025). "Molecular biology and cytology experiments were conducted to validate the potential role of TET3 in tumor progression." (PMID 39104395, 2024). "The results demonstrated higher expression levels of TET3 in all four tumor cell lines compared to the corresponding control cell lines." (PMID 39104395, 2024). "We identified TET1, TET2, and TET3 as pivotal players influencing tumor progression, prognosis, immune response, tumor microenvironment, and drug sensitivity." (PMID 39104395, 2024). "In subsequent experiments, where we selectively silenced TET3 expression in four distinct tumor cell lines (BGC-823, HepG2, A549, TPC-1), we observed a profound attenuation of multiple malignant phenotypes." (PMID 39104395, 2024). "The findings indicated that the therapeutic efficacy of these drugs on tumor cells positively correlated with the expression level of TET3." (PMID 39104395, 2024).